TNF (tumor necrosis factor)
Diseases named in the same sentence as TNF in open-access papers (continued):
Sharing a sentence is not in itself a finding about the gene and the disease.
oral cancer (continued). "The aim of this study was to compare salivary and serum concentrations of IL-1β, IL-6 and TNF-α in patients with oral leukoplakia, oral cancer and healthy controls." (PMID 21743397, 2012). "Serum TNF-α concentrations in control group were significantly higher than serum TNF-α concentrations in patients with oral cancer and leukoplakia (p≤0.05)." (PMID 21743397, 2012). "Serum TNF-α concentrations were significantly higher in control subjects compared to oral cancer patients." (PMID 21743397, 2012). "Moreover, IL-37 mitigated the proliferation induced by LPS and TNF-α, and the KD of IL-37 exacerbated the proliferation triggered by LPS and TNF-α in oral cancer cells." (PMID 40444012, 2025). "Suppress the invasion and migration of oral cancer by downregulating TNF-α-induced NF-κB signaling." (PMID 40672375, 2025). "Moreover, we found that TNFα was highly upregulated in the Sp5C following the induction of oral cancer pain and that intra-Sp5C injection of the PD-1 antibody diminished the upregulation of TNFα." (PMID 39660489, 2025). "Furthermore, IL-37 mitigated the proliferation of oral cancer cells induced by LPS and TNF-α, while the KD of IL-37 exacerbated this proliferation." (PMID 40444012, 2025). "IL-6, TNF-α, and endothelin are established (oral cancer) pain mediators." (PMID 40144515, 2025). "Following this, we found that the levels of TNF-α and IL-10, a well-known biomarker for oral cancer, were significantly augmented in the control group; however, GSK343 treatment modulated these inflammatory players’ release in a concentration-dependent manner, counteracting inflammation." (PMID 39204206, 2024). "Interestingly, TNF-α levels in the plasma of individuals in the control group were found to be greater than those in patients with oral cancer." (PMID 38595736, 2024). "Injection of a TNF-α antagonist can partly block the mechanical hyperalgesia in oral cancer." (PMID 37007073, 2023). "Furthermore, TNF-α is a mediator of pain perception and inflammation in oral cancer, and TNF-α blockade can potentially alleviate oral cancer-related pain." (PMID 37711747, 2023). "Furthermore, it deters TNF-α expression in human oral cancer cells through the ERK and NF-κB pathways." (PMID 38235107, 2023). "The proliferation and invasion of oral cancer is bolstered by tumor-infiltrating pDCs through the activation of the TNF-α/NF-κB/CXCR-4 pathway, which may serve as a potential immunological target for the treatment of OSCCs in the future." (PMID 35740551, 2022). "TNF-α was decreased in ALPK1-depleted metastatic oral cancer cells." (PMID 36139553, 2022). "ELISA results showed that the concentration of TNF-α in LN+ pDC-CM was higher than that in LN- pDC-CM, suggesting that TNF-α secreted by tumor-infiltrating pDC may contribute to NF-κB activation in oral cancer cells." (PMID 33854604, 2021). "Oral cancer- or TNFα-activated Schwann cells promote tumor progression and pain." (PMID 33469141, 2021). "Oral cancer and TNFα can both induce Schwann cell activation." (PMID 33469141, 2021). "To further support our hypothesis, we showed that direct TNF-α stimulation upregulates CXCR-4 expression in an oral cancer Cal 27 cell line via NF-κB activation, and addition of TNF-α neutralizing antibodies could decrease the pDC-CM-mediated NF-κB activation." (PMID 33854604, 2021). "The present study demonstrated that TNFα has a dual function in oral cancer progression and pain." (PMID 33469141, 2021). "Our data support the role of TNFα in promoting oral cancer progression." (PMID 33469141, 2021). "We examined the effect of TNFα antagonism on oral cancer growth in vitro and in vivo." (PMID 33469141, 2021). "We established a role of TNFα in oral cancer-induced chronic pain with several lines of evidence." (PMID 33469141, 2021). "We hypothesize that the oral cancer mediator TNFα activates Schwann cells, which further promotes cancer progression and pain." (PMID 33469141, 2021).
oral cancer (continued). "In patients with oral cancer, local and systemic higher levels of pro-inflammatory cytokines TNF-alpha, IL-6 and IL1-beta may contribute to tumor progression leading to a poor prognosis of the disease." (PMID 33411841, 2021). "Syncytin-1 is an important fusogen that mediates cell–cell fusion, and it was upregulated through the Wnt/β-catenin pathway; thus, we concluded that TNF-α promoted fusion between oral cancer cells and vascular endothelial cells via the Wnt/β-catenin-dependent upregulation of syncytin-1." (PMID 31380426, 2019). "It has been shown that in oral cancer, miR-21 is involved in the regulation of proliferation in cancer cells by inhibition of tumor necrosis factor alpha (TNF-α), and in the upregulation of miR-21, resulting in increased proliferation and decreased TNF-α expression." (PMID 31766478, 2019). "Therefore, despite there is an increased immunoexpression of cytokines in the primary tumour, only TNF-α was the inflammatory cytokine that influenced the survival of patients with oral cancer." (PMID 31870104, 2019). "Together, a concordant increase of HAS3 with TNF-α expression could potentially serve as a poor prognosis signature for oral cancer." (PMID 28107185, 2017). "To examine if TNF-α could increase the in vivo NF-κB binding to the HAS3 promoter in oral cancer cells, we performed ChIP-qPCR analysis of NF-κB sites I and II in P1, III in P2 and IV in P3 promoter regions." (PMID 28107185, 2017). "We examined by qRT-PCR if TNF-α also stimulated HAS3 mRNA expression in oral cancer cells." (PMID 28107185, 2017). "Since TNF-α may function as a upstream mediator for HAS3 expression in oral cancer, we next studied the correlation of TNF-α deregulation with late-stage patients’ clinicopathologic characteristics and clinical outcome." (PMID 28107185, 2017). "Together, HAS3 and TNF-α formed an inter-regulation loop to enhance tumorigenesis in oral cancer." (PMID 28107185, 2017). "However, serum TNF-α concentration was significantly higher in control subjects compared to oral cancer patients." (PMID 27034760, 2016). "Moreover, IL-37 mitigated LPS and TNF-α-induced proliferation and migration of oral cancer cells." (PMID 40444012, 2025). "Similarly, this study found that the STAT3 inhibitor stattic further promoted LPS- and TNF-α-induced increases in cell viability and migration of oral cancer cells, highlighting the crucial role of IL-37 in regulating the growth, proliferation, and migration of oral cancer cells." (PMID 40444012, 2025). "The KD of IL-37 further exacerbated LPS and TNF-α-induced proliferation of oral cancer cells, suggesting that IL-37 may play a crucial role in the activities of various cancer types, including oral cancer." (PMID 40444012, 2025). "Furthermore, GLY extracts suppressed TNF-α level in oral carcinoma cells." (PMID 33498415, 2021). "To examine whether TNFα released into the cancer microenvironment is associated with oral cancer pain in humans, we assessed oral cancer pain using a validated oral cancer pain questionnaire and measured TNFα protein concentration in resected oral tumors in patients." (PMID 33469141, 2021). "However, little is known about the underlying mechanism between TNF-α and TMEN182 in oral cancer." (PMID 30893332, 2019). "Therefore, TNF-α/miR-450a/TMEM182 signaling axis may be a novel potential target for clinical intervention in oral cancer." (PMID 30893332, 2019). "The adipokine Chemerin can enhance the invasiveness of oral cancer cells by activating the STAT3 signaling pathway and promoting the production of IL-6 and TNF-α." (PMID 40282437, 2025). "This study observed that IL-37 exhibited potent inhibitory effects on the TNF-α-induced expression of inflammation-related genes, including IL23, IL1b, IL6, and IL17 in oral cancer cells." (PMID 40444012, 2025).
oral cancer (continued). "In contrast, oral cancer patients demonstrated elevated concentrations of key markers, including CPT1A, IL-6, OXSR1, and TNF-α, reflecting substantial alterations in metabolic and inflammatory pathways." (PMID 39456670, 2024). "Overall, this study highlights the promising role of naringin as a pro-apoptotic and cytotoxic phytochemical regulating the gene expression of Bcl-2, TGF-β, SMAD2, TNFα, NFκB, BAD, BAX, and caspase-3, thereby treating oral cancer." (PMID 39156270, 2024). "Oral cancer cell development and metastasis are strongly impacted by the TGF-β, SMAD2, TNFα, and NFκB signaling pathways." (PMID 39156270, 2024). "This study investigated the impact of naringin on oral cancer cell line mediated by the TGF-β, SMAD2, TNFα, and NFκB signaling pathways." (PMID 39156270, 2024). "In summary, this research emphasizes the potential of naringin as a cytotoxic and pro-apoptotic phytochemical that modulates the expression of Bcl-2, TGF-β, SMAD2, TNFα, NFκB, BAD, BAX, and caspase-3 genes, ultimately aiding the treatment of oral cancer." (PMID 39156270, 2024). "There are several ongoing studies with mAbs in oral cancers related to the key words (“oropharyngeal cancer” OR “oral cancer” OR “oral cavity cancer”) and (“cytokine therapy” OR cytokines OR IFN-α OR IL-2 OR TNF-α) from ClinicalTrials." (PMID 36209263, 2022). "Previous studies have identified an important role of tumor necrosis factor α (TNFα) and TNF receptor 1 (TNFR1) in the invasiveness of oral cancer cell lines." (PMID 34650923, 2021). "Specifically, TNF-α, IL-6, and PGE-2 participate in the process of submucous fibrosis, which plays a critical role in enhancing the malignant transformation of oral cancer cells." (PMID 34445474, 2021). "In contrast, Schwann cells are more activated in the presence of oral cancer cells than precancerous DOK cells, probably due to higher TNFα protein concentration in HSC-3 cells than DOK cells." (PMID 33469141, 2021). "Further comparisons revealed notable elevations of IL-6, IL-8, TNF-α, HCC-1, and PF-4 levels in OSCC collated to OL sample cohorts, with increases traceable from early oral cancer stages." (PMID 33924500, 2021). "TNF-α and HAS3 formed an inter-regulation loop in mediating oral cancer malignancy via NF-κB activation." (PMID 28107185, 2017). "Consistent with a positive role of TNF-α on NF-κB activity and a potential mediation of HAS3 expression by TNF-α, we detected a dose-dependent increase of HAS3 mRNA expression and canonical NF-κB activation in TNF-α-treated oral cancer cells." (PMID 28107185, 2017). "In both tumor-bearing mice and oral cancer patients, heat therapy results in elevated lymphocyte transformation index (LTI), CD4+ cell counts, and significantly increased levels of interleukin-2 (IL-2) and tumor necrosis factor-α (TNF-α) activity." (PMID 39027362, 2024). "Increased TNF-α levels in samples from OSCC patients and oral, potentially malignant, disorders, along with saliva from OSCC patients, underscore TNF-α’s relevance in oral cancer." (PMID 38612423, 2024). "Oral cancer tissues showed significantly elevated levels of the CPT1A protein; an increased presence of T-helper cell counts (CD4+); and higher levels of OXSR1, IL-6, and TNF-α." (PMID 39456670, 2024). "TNFα and NFκB genes are considered markers of KB1 oral cancer cells." (PMID 39435241, 2024). "In most cases, pro-inflammatory cytokines (IFN-γ, IL-2, IL-1α, IL-1β, TNF-α, IL-17, and IL-8), anti-inflammatory cytokines (IL-4 and IL-10), and pro-/anti-inflammatory cytokines (IL-6 and TGF-β) are unbalanced in oral cancer, resulting in an immunosuppressive environment." (PMID 37686542, 2023). "Salivary TNF-α samples have been shown to have the potential for non-invasive monitoring of premalignant conditions during routine oral cancer screening." (PMID 36980727, 2023).
oral cancer (continued). "The TNF-α blockade abolished the IFIT2 depletion-induced sphere formation, indicating that TNF-α may be involved in the CSC-like phenotypes in oral cancer." (PMID 36979874, 2023). "Moreover, a possible topical application for the prevention of oral carcinoma has been theorized on the basis that it would inhibit the inflammatory factors chemokine ligand 1 (CXCL1) and tumor necrosis factor alpha (TNF-α)." (PMID 35052539, 2021). "Previously, we have shown that TNFα is responsible for oral cancer supernatant-induced acute nociception." (PMID 33469141, 2021). "Understanding the inter-regulation of HA, TNF-α, and HAS3 in oral cancer might facilitate the development of novel therapeutics for treating this disease and many other critical diseases associated with HA deregulation." (PMID 28107185, 2017). "The increased TNF-α expression was also observed in HAS3-overexpressing oral cancer cells by qRT-PCR (data not shown)." (PMID 28107185, 2017). "The intimate contact between the buccal mucosa and the AQ during chewing induces chronic and abnormal mucosa inflammation by promoting the release of inflammatory mediators like IL-6, TNF-α, and PGE2 by oral keratinocytes, playing a crucial role in the pathogenesis of oral cancer." (PMID 28209200, 2017). "In addition to TNF-α-mediated HAS3 transcriptional induction, chronic TNF-α exposure induced oral cancer cell stemness." (PMID 28107185, 2017). "In addition, TNF-α, a proinflammatory cytokine, upregulated AID expression in the HSC-2 oral cancer cell line." (PMID 23634222, 2013). "Furthermore, we investigated whether the predicted candidate miRNAs, which are downregulated in oral cancer and are predicted to be targets of LINC00944, could regulate key mRNAs involved in the TNF-α/NF-κB signaling pathway." (PMID 39941858, 2025). "TNF-α is worthy of particular attention in OSCC, with its presence demonstrated to enhance cell proliferation and its downregulation demonstrated to inhibit proliferation and migration in other carcinomas in both in vitro and in vivo models and oral cancer patients." (PMID 36980727, 2023). "TNFα inhibition reduces oral cancer growth and cancer-induced nociceptive behavior." (PMID 33469141, 2021). "TNF-α upregulated the expression of VCAM-1 in vascular endothelium, which is a ligand of very late activation antigen 4 (VLA-4) on cancer cells, and finally enhanced the adhesion and fusion between oral cancer cells and vascular endothelial cells through the VCAM-1/VLA-4 pathway." (PMID 31380426, 2019). "Among the most frequent cytokines investigated as candidates for OSCC biomarkers, IL-6, IL-8, TNF-α are present at higher concentration in the saliva of OSCC patients than in healthy controls and may therefore serve as basis for the development of rapid tests for early diagnosis of oral cancer." (PMID 34202728, 2021). "Recently, we have established a new direct link between inflammation and oral cancer invasion by showing that neutrophils increase OSCC invasion, matrix degradation, and invadopodia formation, independent of direct contact, through a TNFα-dependent mechanism." (PMID 30018735, 2018).
Abdominal obesity (104 papers, 2006 to 2025). Excessive fat around the stomach and abdomen. "Multivariate logistic regression analysis revealed a significant association between TNF-α concentration and the risk of abdominal obesity measured by WHtR (Model 2, OR = 1.429, 95% CI = 1.005–2.031, p = 0.047)." (PMID 40137151, 2025). "For example, tumor necrosis factor and interleukin 6 play a role in promoting osteoclast differentiation, but these factors are associated with abdominal obesity." (PMID 37805606, 2023). "In conclusion, our results revealed the interaction of central obesity and the clustering of the other MetS cardiometabolic risk factors for exacerbating circulatory TNF-α and leptin; and reducing adiponectin." (PMID 30114249, 2018). "The interacting effect of central obesity with all of the other four MetS risk factors increased the proinflammatory status of adipokines (TNF-α, leptin) and decreased the anti-inflammatory status of adipokine (adiponectin)." (PMID 30114249, 2018). "For subjects with central obesity, the clustering of 4 risk factors was associated with an increase in TNF-α concentration." (PMID 30114249, 2018). "Our results indicated that the interaction effects between central obesity and the clustering of other 4 MetS cardiometabolic risk factors existed for TNF-α, adiponectin and leptin." (PMID 30114249, 2018). "Abdominal obesity, a key component of MetS, is consistently associated with major increases in pro-inflammatory adipocytokines, such as TNF-α, IL-6, hsCRP or PAI-1 active, as well as reduced protective cytokines, such as adiponectin, agreeing with our data." (PMID 25407698, 2014). "However, a significant association between TNF-α and abdominal obesity, expressed as the waist-to-height ratio (WHtR), was observed in Model 2 (OR = 1.429, 95% CI: 1.005–2.031, p = 0.047)." (PMID 40137151, 2025). "The mechanism behind this could be due to pro-inflammatory cytokines associated with abdominal obesity, such as tumor necrosis factor-alpha and interleukin-6 (IL-6)." (PMID 37764873, 2023). "Interaction effects between central obesity and the clustering of the other 4 MetS cardiometabolic risk factors were found for TNF-α (Wald chi square = 5.47, P = 0.019), leptin (Wald chi square = 4.92, P = 0.027) and adiponectin (Wald chi square = 9.17, P = 0.002)." (PMID 30114249, 2018). "A study conducted on the Swiss population found that obese individuals exhibited elevated levels of hypersensitive C-reactive protein (hs-CRP), whereas those with abdominal obesity showed increased levels of TNF-α." (PMID 40612555, 2025). "TNF-α showed significant positive correlations with waist circumference (r = 0.28, p = 0.002) and ALT (r = 0.019, p = 0.03), indicating associations with central obesity and hepatocellular injury." (PMID 41590632, 2025). "The explanation for the correlation of neck circumference and blood pressure is that central obesity as reflected by increased neck circumference gives rise to the release of some inflammatory cytokines such as tumor necrosis factor-α and IL-6." (PMID 40519810, 2025). "The role of TNF-α as a promoter of central obesity results from its effects on lipolysis and the inhibition of insulin signalling in adipose tissue, leading to localized inflammation and enhanced fat accumulation." (PMID 40137151, 2025). "Central obesity leads to excessive secretion of pro-inflammatory mediators like leptin, TNF-α, and IL-6, thus escalating systemic inflammation and vascular injury." (PMID 40606025, 2025). "Heightened secretion of IL-6, TNF α, and C-RP is evident in individuals with abdominal obesity, intensifying the inflammatory state." (PMID 40310144, 2025). "Abdominal obesity is characterized by an excess of visceral fat, which secretes pro-inflammatory cytokines such as TNF-α, IL-6, and CRP." (PMID 39450238, 2024).